KRAS (KRas proto-oncogene, GTPase)
Diseases named in the same sentence as KRAS in open-access papers (continued):
Sharing a sentence is not in itself a finding about the gene and the disease.
endometriosis (continued). "In total, 52.5% (64/122) of the subjects had at least one endometriosis sample with a KRAS mutation, while 47.5% (58/122) had no KRAS mutations in any of the endometriosis samples assayed." (PMID 36977195, 2023). "The rate of re‐operation (for endometriosis) was low in the cohort overall (13.9%; 17/122), with 17.2% (11/64) of subjects with KRAS mutation and 10.3% (6/58) of subjects without KRAS mutation having a re‐operation (RR = 1.66, 95% CI: 0.66–4.21)." (PMID 36977195, 2023). "KRAS mutation status for each subject was coded as present (KRAS mutation in at least one endometriosis sample in a subject) or absent." (PMID 36977195, 2023). "Work presented here suggests the KRAS axis may be a relevant target to reduce the invasiveness, spread, or burden of endometriosis." (PMID 36977195, 2023). "Moreover, different types of gene-based biomarkers such as ARID1A, PIK3CA, KRAS and CTNNB1 are recurrently mutated in endometrial cancer type I, endometriosis and endometriosis-associated ovarian tumors." (PMID 37189525, 2023). "In fact, these have mutations in common with endometriosis, such as PTEN, PIK3CA, KRAS and ARID1A." (PMID 37189525, 2023). "In the first case, we identified de novo activating PIK3CA and KRAS mutations in endometrioid cancer lesions but not in endometriosis." (PMID 35359373, 2022). "Furthermore, the co-occurring gain of function mutations of KRAS with the PIK3CA p.H1047 is frequently observed in both adenomyosis and endometriosis." (PMID 35203298, 2022). "In the first case, we identified de novo activating mutations in PIK3CA and KRAS in endometrioid cancer lesions but not in endometriosis." (PMID 35359373, 2022). "Recent comprehensive analyses have shown that pathological mutations in cancer-related genes such as KRAS and PIK3CA are frequently observed in endometriosis, and these oncogenic abnormalities may lead to high expression of TF and IL6 in endometriosis." (PMID 35565252, 2022). "Elevated KRAS expression was described in the eutopic endometrium of patients with endometriosis." (PMID 36612107, 2022). "Our results converge with other reports, where cancer-related mutations were found in endometriosis without cancer, particularly recurrent KRAS mutations." (PMID 33805315, 2021). "Our results converge with other reports, where cancer-related mutations were found in endometriosis without cancer, in particular recurrent KRAS mutations." (PMID 33805315, 2021). "Furthermore, KRAS has been shown to be a prevalent biomarker in the endometrium of women with endometriosis." (PMID 32033052, 2020). "Let-7b treatment of endometriosis could decrease inflammatory signaling (IL-6), decreased estrogen signaling (ER and Cyp19A1), and also decrease KRAS." (PMID 32850438, 2020). "For instance, drugs that target PIK3CA or MEK signals, such as alpelisib or trametinib, respectively, may theoretically offer new options for women suffering with endometriosis, which harbors mutations in PIK3CA or KRAS." (PMID 32066498, 2020). "KRAS therefore likely participates in the pathogenesis of endometriosis." (PMID 29750165, 2018). "KRAS has been proposed as a strong candidate gene in the pathophysiology of endometriosis." (PMID 28754906, 2017). "Interestingly, the levels of KRAS protein were significantly increased in the stromal and epithelial cells of endometrium from proliferative and secretory phase endometriosis patients (n = 52) as compared to control patients (n = 17)." (PMID 28754906, 2017). "The authors propose that KRAS mutations may serve as potential targets for non-hormonal therapeutic strategies in endometriosis." (PMID 39859551, 2025). "Secondary SCC may also arise from non-squamous ovarian tumors such as mucinous neoplasms or endometriosis, exhibiting mutations such as KRAS and PTEN, with subsequent squamous differentiation." (PMID 39735155, 2024).
endometriosis (continued). "The presence of PIK3CA- or KRAS-mutated clones in histologically normal uterine endometrium in endometriosis but also in patients without endometriosis has also been demonstrated, so the theory of the cellular origin of endometriosis requires further investigation." (PMID 37005590, 2023). "KRAS mutations may serve as a nonhormonal therapeutic target and contribute to a molecularly informed classification in endometriosis." (PMID 36977195, 2023). "In summary, this is the first time that non-mutated KRAS activation has been shown to be strongly correlated with endometrium-associated endometriosis and that this activation triggers specific changes in histone deacetylase, SIRT1 which we postulate is a key driver of P4 resistance." (PMID 28754906, 2017). "However, in human endometriosis, no KRAS mutations have been found, and alterations of PTEN have been found in only 20% of the cases." (PMID 19055724, 2008). "In addition, KRAS mutations were detected in coexisting endometriosis and normal endometrium in several subjects, suggesting that both adenomyosis and endometriosis may originate from normal endometrial tissue." (PMID 40679511, 2025). "On the other hand, overexpression of KRAS and the histone deacetylase SIRT1 has been observed in the eutopic endometrium with endometriosis." (PMID 35203298, 2022). "KRAS can be activated by many factors including TGF-β, EGF, PDGF which are activated in endometriosis." (PMID 36612107, 2022). "Gene alterations found in both endometriosis and clear-cell ovarian carcinoma include genes such as PIK3CA, PTEN, ERBB2, KRAS, ARID1A, PPP2R1A, MLH1, and CTNNB1." (PMID 35563789, 2022). "The authors suggest that KRAS, SIRT1, and BCL6 are coordinately over-expressed in the eutopic endometrium of women with endometriosis and likely participate in the pathogenesis of endometriosis." (PMID 33435147, 2021). "In the current study, we aimed to comprehensively analyze the roles of KRAS and PIK3CA oncogenes in endometriosis." (PMID 34202354, 2021). "Microarray gene-expression analysis revealed several genes that demonstrated correlations with KRAS or PIK3CA invasion-specific gene signatures, which played essential roles in activating the endometriosis progression pathways." (PMID 34202354, 2021). "Genetic alterations involving genes such as KRAS, PIK3CA, PPP2R1A and ARIDIA have been detected in eutopic endometrium and in endometriosis and adenomyosis lesions, suggesting that both eutopic and ectopic endometrium are clonally related." (PMID 34681634, 2021). "A recent study demonstrated a KRAS activation-triggered SIRT1 overexpression in women with endometriosis, which has been suggested to contribute to infertility and the pathogenesis of endometriosis." (PMID 34744791, 2021). "Furthermore, galectin-3 has been shown to interact with KRAS protein and contribute to cellular growth, proliferation, inflammation, and the uptake of nutrients in endometriotic lesions and may be involved in the maintenance and propagation of endometriosis." (PMID 32033052, 2020). "Importantly, it has been reported that, with regard to perimenopausal endometriosis, endometrioid ovarian carcinomas (ENOC) and clear cell ovarian carcinomas (CCOC) are associated with mutations of ARID1A, a tumor suppressor gene, PTEN, KRAS and -catenin (CTNNB1) genes." (PMID 30870972, 2019). "Together, these data suggest that KRAS, SIRT1 and BCL6 are coordinately over-expressed in eutopic endometrium of women with endometriosis and likely participate in the pathogenesis of endometriosis." (PMID 28754906, 2017). "In this study, we investigated the levels of KRAS and SIRT1 proteins in eutopic endometrium from women with endometriosis." (PMID 28754906, 2017).
endometriosis (continued). "Here we report coordinated activation of KRAS and over-expression of Sirtuin 1 (SIRT1), a histone deacetylase and gene silencer, in the eutopic endometrium from women with endometriosis throughout the menstrual cycle." (PMID 28754906, 2017). "Since endometrium from apparently healthy women could also harbor KRAS mutations, which confer proliferative advantage without causing any overt pathology, we have thus argued that all endometrial aberrations reported so far are neither sufficient nor necessary to cause endometriosis or adenomyosis." (PMID 38254632, 2023). "Furthermore, ovarian endometrioid cancer shares similar gene alterations with endometriosis, including PIK3CA, PTEN, KRAS, and ARID1A." (PMID 35563789, 2022). "However, there were also identified mutated genes that were characteristic for each group: JAK3, KRAS and RB1 for endometriosis; and ATM, BRAF, CDH1, EGFR, NRAS, RET and SMO for ovarian ENOC." (PMID 36612107, 2022). "Additionally, they reported coordinated activation of KRAS (Kirsten rat sarcoma virus) and over-expression of SIRT1, a histone deacetylase and gene silencer, in the eutopic endometrium from women with endometriosis throughout the menstrual cycle." (PMID 33435147, 2021). "Ideally, the status of KRAS- and/or PIK3CA-mutated clones in histologically normal endometrium (NE) should be compared between individuals with and without endometriosis." (PMID 31857578, 2019). "Although age did not correlate with frequency of KRAS mutations in our cohort, it would be intriguing to determine whether these factors are also relevant in the contexts of adenomyosis and endometriosis, a question demanding future studies using a larger patient cohort." (PMID 31857578, 2019). "A KRAS mutation has been detected in OEC tissue, but not in atypical endometriosis bordering the cancerous region." (PMID 29599905, 2018). "In general, both endometrioid and clear cell ovarian cancer with or without endometriosis have common high frequency mutations in ARID1A, PIK3CA, catenin betat 1 (CTNNB1), PTEN, and KRAS." (PMID 30087267, 2018). "Thus, inhibition of KRAS/PIK3CA, or their downstream targets such as LOX or PTX3 inhibitors, might be clinically effective in progestin-resistant endometriosis-related pain." (PMID 38666954, 2024). "Interestingly, somatic driven mutations in KRAS, PTEN, PIK3CA and ARID1A have been also observed in more than 26% of cases of deep infiltrating endometriosis lesions, which are associated with virtually no risk of malignant transformation." (PMID 35457244, 2022). "Furthermore, one study showed that recurrently mutated cancer driver genes, such as KRAS, PIK3CA, PPP2R1A, and ARID1A, are also present in endometriosis without cancer association." (PMID 34202354, 2021). "For example, some known somatic driver mutations in the genes ARID1A, PIK3CA, KRAS, and PPP2R1A have been found in the endometriotic lesions of 19 of 24 patients with deep-infiltrating endometriosis even though this form of endometriosis almost never undergoes malignant transformation." (PMID 29945886, 2018). "The levels of SIRT1 and KRAS were compared in endometrium of women with and without endometriosis." (PMID 28754906, 2017). "Thus, endometrial clones bearing KRAS and/or PIK3CA mutations may not necessarily drive the pathogenesis of endometriosis." (PMID 31857578, 2019). "Of note, KRAS mutations have been suggested to distinguish endometroid carcinomas that are related to endometriosis from those that are not related to endometriosis further indicating that KRAS status may indeed signify biologically and clinically relevant subgroups of endometroid carcinoma." (PMID 23800114, 2013). "To determine the cell-specific expression of KRAS and SIRT1, we performed immunohistochemical analysis in endometrium from women with and without endometriosis." (PMID 28754906, 2017).
endometriosis (continued). "In control women KRAS and SIRT1 proteins were weakly detected in the stromal and epithelial cells of endometrium from the proliferative phase and early, mid, and late secretory phases in women without endometriosis (n ≥ 4 per phase)." (PMID 28754906, 2017).
thyroid cancer (86 papers, 2008 to 2026). "After BRAF, activating mutations of RAS (NRAS >> HRAS > KRAS) are the next most common oncogenic drivers found in advanced thyroid cancers." (PMID 39874138, 2025). "For instance, thyroid cancers which had mutations in codons 12 or 13 of KRAS were found to be associated with comparatively lower malignant outcomes (41.7%) as compared to mutations in codon 61 of NRAS (86.8%) and codon 61 of HRAS (95.5%)." (PMID 39941320, 2025). "In this aggressive form of thyroid cancer, mutations in KRAS can lead to constitutive activation of the RAS/MAPK pathway." (PMID 40141222, 2025). "Molecular profiling using our custom thyroid cancer gene panel revealed the molecular characteristics of this tumor, which showed additional mutations (KRAS and TERT‐p) in In‐N, indicating STc with malignant potential from the well‐differentiated Out‐N." (PMID 41090246, 2025). "BRAF is the most commonly mutated gene, and KRAS mutations are the second most common genetic alterations in well-differentiated thyroid cancers." (PMID 37185420, 2023). "The three isoforms of RAS (HRAS, NRAS, and KRAS) mutations are the second most common mutation encountered in thyroid carcinomas." (PMID 35197932, 2022). "DN200434, the recently discovered orally bioavailable agonist of ESRRG, enhanced radioiodine therapy responsiveness in thyroid cancer with either KRAS or BRAF mutations both in vitro and in vivo." (PMID 32571331, 2020). "This is noteworthy because BRAF mutation is recognized as risk factor for thyroid cancer progression and because, so far, KRAS proteins have proved very difficult to be directly targeted." (PMID 27058903, 2016). "Consistently, we reported high KRAS prevalence and this may be higher since we reported KRAS mutations only in BRAF-negative thyroid cancer samples." (PMID 36510281, 2022). "There may be a role for targeted inhibitors of the RAS/MAPK pathway in MLAs, given their underlying KRAS mutations and a clinical study had shown that thyroid carcinomas with KRAS mutations were very sensitive to lenvatinib." (PMID 35865471, 2022). "However, resistance to OTX008 can be observed in the KRAS mutated line, suggesting crosstalk between Gal-1 and KRAS for signal transduction in thyroid cancer cells." (PMID 34063063, 2021). "Therefore, we conducted functional study using thyroid cancer cells with RAS mutation (KRAS mutation in Cal62 and HRAS mutation in HTH83) because high MFN2 expressed PTC are related with RAS-like gene expression." (PMID 33479369, 2021). "Among the genes associated with thyroid cancer BRAF, RAS, KRAS, NRAS, PTEN, and PRKAR1A genes participate in regulating oxidative metabolism." (PMID 39180118, 2024). "-The clinical utility of BRAF, KRAS, NRAS, and TERT promoter mutation analysis on ctDNA appeared to be limited to early-stage thyroid cancers." (PMID 37762070, 2023). "Of note, EIF1AX mutations were found almost exclusively in HRAS-, KRAS-, and NRAS-mutant thyroid cancers (p<0.05), whereas STK11 mutations were found in greater proportion of HRAS-mutant NSCLC compared to the other HRAS-mutant cancer types." (PMID 37503077, 2023). "Two of the most important and common mutations found in thyroid cancer are BRAFV600E mutations and RAS-like mutations, which involve a family of three highly homologous isoforms (NRAS, KRAS and HRAS)." (PMID 35246262, 2022). "In the thyroid cancer samples BRAF mutations co-occurred less frequently than expected with mutations in NRAS, HRAS, RET, PTEN, NF1 and KRAS." (PMID 36275468, 2022). "RAS mutations (including its variants, including NRAS, KRAS, and HRAS) are the most commonly mutated genes in thyroid cancer." (PMID 36613811, 2022).
thyroid cancer (continued). "As a motivating example, other studies have shown that activating mutations in Ras isoforms (HRAS, KRAS, NRAS) tend to have similar effects to one another in thyroid cancer, producing similar gene expression signatures." (PMID 35761387, 2022). "Although KRAS and EGFR mutations have been well investigated in NSCLC, however, study of these mutations on thyroid carcinoma is still limited." (PMID 36510281, 2022). "Samples were obtained from the archive between 2013 and 2019 and used to investigate BRAF, KRAS, and EGFR mutations in thyroid carcinoma samples." (PMID 36510281, 2022). "Thirty-two somatic mutations were identified exclusively in known thyroid cancer genes (BRAF, KRAS, NRAS, and TERT)." (PMID 33821390, 2021). "Genetic and epigenetic alteration of the RAS–RAF–MEK–MAPK–ERK pathway, and mutations in NRAS, KRAS, and BRAF, have been shown to strongly influence the development of thyroid cancers." (PMID 33915745, 2021). "The clinical utility of BRAF, KRAS, NRAS, and TERT promoter mutation analysis on ctDNA appears to be limited to early-stage thyroid cancers." (PMID 33915745, 2021). "Limited data are available on the diagnostic utility of circulating tumor DNA (ctDNA) in early-stage thyroid cancers for BRAF, KRAS, NRAS, and TERT promoter mutations, which are known detectable markers for thyroid cancers." (PMID 33915745, 2021). "In this study, 73 matched neoplastic tissue and plasma DNA samples and 54 plasma DNA samples from healthy individuals were examined for the diagnostic utility of ctDNA in thyroid cancers focusing on BRAF, KRAS, NRAS, and TERT promoter mutations." (PMID 33915745, 2021). "Only 10% percent of rats whose thyroid was injected with a retrovirus carrying mutant KRAS developed thyroid carcinomas of very small size and with a one-year latency." (PMID 34359686, 2021). "It has been shown that gal-3 interaction with KRAS potentiates thyroid cancer progression, increasing KRAS signaling and thus proliferation." (PMID 29463063, 2018). "RAS mutations (KRAS, NRAS, and HRAS) are found at a relative low frequency in differentiated thyroid cancers compared with the more common BRAF mutations." (PMID 27127178, 2016). "The highly mutated genes (KRAS, HRAS, NRAS, etc.)in somatic cells of thyroid cancer were rarely observed to mutate in patients’ blood in our study." (PMID 26530882, 2015). "Our findings contrast with a recent report showing a positive correlation between a KRAS or BRAF mutation and clinical aggressiveness in colorectal, non-small-cell lung, and thyroid cancers." (PMID 19018267, 2008). "A meta-analysis including 2552 thyroid cancer patients from 17 studies reported an overall RAS mutation prevalence of 35.4% (95% CI: 22.7–50.7%), with NRAS being the most frequent subtype (69.5%), followed by HRAS (25.8%) and KRAS (6.9%)." (PMID 41595518, 2026). "Additionally, studies have reported that PIK3 CA, TERT, and KRAS genes often exhibit methylation-mediated silencing in various cancer types, including thyroid cancer, contributing to the development of a malignant phenotype." (PMID 40450370, 2025). "Interestingly, thyroid cancer alone was found to have a similar statistical significance for the ‘KRAS Signaling Down’ pathway (P < .0001, FDR < 0.0001) in the PSG+ versus PSG− groups." (PMID 40257008, 2025). "Unlike some other cancers, like colorectal or thyroid cancer, where a single-point mutation (like KRAS rs#112445441 or BRAF V600E) is found in a large proportion of samples, in NMSC, there is no single mutation that is seen in a large number of samples." (PMID 38920684, 2024). "We observed that KRAS mutation occurred in 41.3% of the BRAF negative thyroid cancer samples, and 52.6% of it was found in follicular thyroid carcinoma." (PMID 36510281, 2022).